Y_RNA (Y RNA )
Gene: Miscellaneous RNA gene on chromosome 14 (38,987,281 to 38,987,383, forward strand). Ensembl gene ENSG00000199285.
Homologues: Orthologues: chimpanzee Y_RNA (99% identical), guinea pig Y_RNA (87% identical), macaque Y_RNA (81% identical). Paralogues in human: Y_RNA (86% identical), RNY1P5 (85% identical), Y_RNA (85% identical), Y_RNA (84% identical), Y_RNA (83% identical), RNY1P6 (82% identical), Y_RNA (82% identical), Y_RNA (81% identical), RNY1 (80% identical), RNY1P1 (80% identical), Y_RNA (80% identical), RNY1P2 (79% identical), and 97 more.